AHDC1 (AT-hook DNA binding motif containing 1)
Description:
Transcription factor required for the proper patterning of the epidermis, which plays a key role in early epithelial morphogenesis. Directly binds promoter and enhancer regions and acts by maintaining local enhancer-promoter chromatin architecture. Interacts with many sequence-specific zinc-finger transcription factors and methyl-CpG-binding proteins to regulate the expression of mesoderm genes that wire surface ectoderm stratification.
Synonyms: DJ159A19.3; RP1-159A19.1; MRD25; XIGIS
Tractability: PROTAC: UniProt records ubiquitination sites on it; ubiquitination databases record sites on it; its protein half-life has been measured.
Gene: Protein-coding gene on chromosome 1 (27,534,035 to 27,604,431, reverse strand). Ensembl gene ENSG00000126705.
Subcellular location: Nucleus; Chromosome
Subcellular location (Human Protein Atlas): Nucleoplasm
Gene Ontology:
Molecular function: DNA-binding transcription factor activity; promoter-enhancer loop anchoring activity; protein binding
Biological process: mesoderm formation; skin morphogenesis; regulation of DNA-templated transcription
Cellular component: chromosome; nucleoplasm; nucleus
Genetic constraint (gnomAD): Loss-of-function variants: 7 observed, 78.35 expected, observed/expected ratio (o/e) 0.0893, 90% interval 0.05 to 0.17. The upper end of that interval is the gene's LOEUF score, 0.17, which puts it in group 1 of 6, group 1 being the genes least tolerant of losing a copy. Missense variants: 1,838 observed, 2,153 expected, observed/expected ratio (o/e) 0.85, 90% interval 0.82 to 0.89. Synonymous variants: 1,049 observed, 980.64 expected, observed/expected ratio (o/e) 1.07, 90% interval 1.02 to 1.13.
Gene-disease validity (ClinGen):
ClinGen rates the evidence that AHDC1 causes each of these diseases.
AHDC1-related intellectual disability - obstructive sleep apnea - mild dysmorphism syndrome (autosomal dominant): Definitive.
Homologues: Orthologues: chimpanzee AHDC1 (99% identical), macaque AHDC1 (99% identical), pig AHDC1 (97% identical), guinea pig AHDC1 (97% identical), mouse Ahdc1 (95% identical), rat Ahdc1 (94% identical), rabbit AHDC1 (72% identical), tropical clawed frog ahdc1 (47% identical), zebrafish ahdc1 (29% identical).
Diseases named in the same sentence as AHDC1 in open-access papers:
AHDC1 is named in the same sentence as 37 diseases in open-access papers, as found by Europe PMC text mining. Sharing a sentence is not in itself a finding about the gene and the disease. The quoted sentences say what the papers report.
Xia-Gibbs syndrome (9 papers, 2021 to 2025). "De novo nonsense or frameshift mutations in the AHDC1 gene have been identified as the causative factor for Xia-Gibbs syndrome (XGS, OMIM#615829) in 2014, a neurodevelopmental disorder characterized by intellectual disability and developmental delay." (PMID 39835152, 2024). "Our labeled dataset contained 23 benign variants of AHDC1 variants, and three variants that are causal for mental retardation (Xia-Gibbs syndrome, OMIM #615829) and hence labeled as pathogenic in brain tissue." (PMID 39285047, 2024). "AHDC1 has been revealed as a responsible gene in Xia-Gibbs syndrome patients, which causes an autosomal dominant multisystem developmental disorder." (PMID 36194562, 2022). "According to the Authors, these cell models were deposited on the hpscreg.eu platform and may provide a useful tool for studying the pathogenesis of Xia-Gibbs syndrome caused by the AHDC1 gene." (PMID 40844525, 2025). "The Xia-Gibbs syndrome has been identified as a de novo heterozygous truncating mutation of AHDC1." (PMID 36194562, 2022). "Similarly, AHDC1 is most probably involved in DNA binding, and loss-of-function mutations result in Xia-Gibbs syndrome—a neurodevelopmental disorder with rare presentation of hearing loss." (PMID 35580588, 2022). "AHDC1 represents a gene of significant interest and importance, not only in the context of neurodevelopmental disorders like Xia-Gibbs syndrome but also in broader biological and pathological processes such as development, differentiation and schizophrenia." (PMID 40844525, 2025). "Xia-Gibbs syndrome (XGS, OMIM #615829) is a rare neurodevelopmental disorder caused by de novo autosomal dominant nonsense and frameshift variants in the AT-Hook DNA-Binding Motif-Containing 1 (AHDC1) gene, most of which lead to truncated protein synthesis." (PMID 39648204, 2025). "Xia-Gibbs syndrome (XGS; MIM: 615829) is a phenotypically heterogeneous neurodevelopmental disorder (NDD) caused by newly arising mutations in the AT-Hook DNA-Binding Motif-Containing 1 (AHDC1) gene that are predicted to lead to truncated AHDC1 protein synthesis." (PMID 34950897, 2021). "Among these, AHDC1 stands out as a top-ranking gene in the SFARI database due to its role in the rare and likely underestimated neurodevelopmental disorder, Xia-Gibbs syndrome (XIGIS)." (PMID 40844525, 2025).
Intellectual disability (7 papers, 2019 to 2025). "Where clinical data were available, individuals with missense mutations all displayed phenotypes consistent with those observed in individuals with AHDC1 truncating mutations, including delayed motor milestones, intellectual disability (ID), hypotonia, and speech delay." (PMID 34950897, 2021). "A de novo balanced translocation with a breakpoint in AHDC1 intron 1 that disrupted the 5′UTR of AHDC1 has been identified in a 5-year-old male patient with developmental delay and intellectual disability." (PMID 31737670, 2019). "Notably, AHDC1 shares conserved sequence similarities with NEXMIF, a protein associated with intellectual disability when mutated, and REV3L, the catalytic subunit of polymerase zeta involved in DNA repair and genome stability." (PMID 40844525, 2025).
cervical cancer (4 papers, 2020 to 2022). A primary or metastatic malignant neoplasm involving the cervix. "In another context, LINC01133 promotes the progression of cervical cancer by sponging miR-4784 to cause the up-regulation of AT-hook DNA-binding motif-containing protein 1 (AHDC1) promoting EMT." (PMID 34445100, 2021). "LINC01133 was found to be primarily located in the cytoplasm of cervical cancer cells, wherein it binds to miR-4784 and competitively inhibits the binding of AHDC1 mRNA to miR-4784." (PMID 35747817, 2022).
developmental delay (4 papers, 2019 to 2025). "While the AHDC1 mutation is likely the source of developmental delay, creation of a genetrap construct in exon 13 of the mouse Matr3 gene revealed a key role for Matr3 in cardiovascular development." (PMID 34350653, 2022). "De novo loss‐of‐function mutations in AHDC1 gene cause Xia‐Gibbs syndrome, a recently described genetic disorder characterized by failure to thrive, hypotonia, global developmental delay, and mild dysmorphic features including hypertelorism, a broad forehead, flat nasal bridge, and thin upper lip." (PMID 30729726, 2019). "Genetic examination of a novel proband exhibiting developmental delay and cardiovascular defects including PDA revealed mutations in both AHDC1 and Matrin 3 (MATR3)." (PMID 34350653, 2022).
Obesity (4 papers, 2024 to 2025). Accumulation of substantial excess body fat. "We recently discovered that mice with Ahdc1 deficiency exhibit notable obesity and energy metabolism disruption." (PMID 39835152, 2024). "AHDC1 has also been linked to metabolic regulation and obesity." (PMID 40844525, 2025). "For example, AHDC1 gene mutations have been discovered in patients with syndromic obesity." (PMID 39835152, 2024). "Compared with the littermate wild-type mice (Ahdc1+/+), Ahdc1+/− mice had significantly lower levels of AHDC1 mRNA expression in the liver, hypothalamus, and cerebral cortex, with the most obvious phenotype related to obesity." (PMID 40844525, 2025). "Interestingly, in a recent study, Li and colleagues established an Ahdc1± mouse strain that exhibited obesity, hyperleptinemia, insulin resistance, abnormal glycolipid metabolism, and hepatic steatosis, which suggest that Ahdc1 may be a key regulator of obesity and energy metabolism." (PMID 40501103, 2025).
epilepsy (2 papers, 2024 to 2025). A brain disorder characterized by episodes of abnormally increased neuronal discharge resulting in transient episodes of sensory or motor neurological dysfunction, or psychic dysfunction. "Additionally, our findings provide statistically significant support for previously reported genotype–phenotype associations between pathogenic variants in the first half of the AHDC1 coding region and the occurrence of epilepsy and scoliosis." (PMID 40501103, 2025). "Additionally, we corroborate the association between causal variants in the first half of the AHDC1 coding region and the manifestations of epilepsy and scoliosis, as well as suggest a novel association with developmental regression." (PMID 40501103, 2025).
schizophrenia (2 papers, 2019 to 2025). A major psychotic disorder characterized by abnormalities in the perception or expression of reality. "One study reports a patient diagnosed with schizophrenia at around 13 years of age who carried a de novo nonsense mutation in the AHDC1 gene." (PMID 40844525, 2025). "We have identified two studies in which mutations in AHDC1 have been in some way associated with schizophrenia, providing support to the idea that AHDC1 might also be one of the molecular factors at the basis of the aetiology of both disorders." (PMID 40844525, 2025). "Two missense mutations in AHDC1 were found to be associated with schizophrenia and oral developmental disorders that might lead to upper airway dysfunction and perhaps OSA." (PMID 31737670, 2019). "Two missense mutations in AHDC1 were found to be associated with schizophrenia and oral developmental disorders that may lead to upper airway dysfunction and perhaps OSA." (PMID 31737670, 2019).
Sleep apnea (2 papers, 2019 to 2023). An intermittent cessation of airflow at the mouth and nose during sleep is known as sleep apnea. "In the present study, MalaCards database suggests an important gene associated with sleep apnea is AHDC1, and among its related pathways/superpathways are signaling by GPCR and respiratory electron transport, ATP synthesis by chemiosmotic coupling, and heat production by uncoupling proteins." (PMID 31737670, 2019).
COVID-19 (1 paper, 2022). A disease caused by infection with severe acute respiratory syndrome coronavirus 2. "In this study, we found 14 other diseases associated with COVID-19 by sharing four DEGs (i.e., DMD, C2CD3, WNT3, and AHDC1) most prevalent in COVID-19." (PMID 36059456, 2022). "In addition, we identified 14 other diseases associated with COVID-19 by sharing four DEGs (i.e., DMD, C2CD3, WNT3 and AHDC1) which were most prevalent in COVID-19." (PMID 36059456, 2022).
Ewing sarcoma (1 paper, 2022). A small round cell tumor that lacks morphologic, immunohistochemical, and electron microscopic evidence of neuroectodermal differentiation. "Together, we suggest that AHDC1 is one of the transcriptional co-regulators of EWS-ETS fusion proteins in Ewing’s sarcoma cells." (PMID 36194562, 2022). "We also tested whether AHDC1 knockdown reduces protein expression levels in other Ewing’s sarcoma cell lines." (PMID 36194562, 2022). "In addition, SAOS-2 and U-2 OS osteosarcoma cell lines did not alter any growth defects after shAHDC1 knockdown, suggesting that AHDC1 affects cell growth in Ewing’s sarcoma cells." (PMID 36194562, 2022). "To test whether AHDC1 affects cell growth in Ewing’s sarcoma cells, we transduced shAHDC1-expressing lentivirus in A673 cells." (PMID 36194562, 2022). "Although the protein size of the Gibbin and AHDC1 protein that we analyzed are different, we guess that AHDC1 might be one of the hubs between enhancers and promoters in the Ewing sarcoma cells and partially affect gene expression of the EWS-ETS fusion proteins." (PMID 36194562, 2022). "Thus, AHDC1 may be one of the regulators for oncogenic function in Ewing’s sarcoma cells." (PMID 36194562, 2022). "We hypothesize that AHDC1 might be one of the accessory proteins needed to stabilize BRD4, BRG1, and probably EWS-FLI1 in Ewing’s sarcoma cells." (PMID 36194562, 2022). "In addition, FLAG-tagged AHDC1 expression partially co-localized with BRD4 and BRG1 in Ewing’s sarcoma cells." (PMID 36194562, 2022). "In addition, AHDC1 knockdown showed reduced cell growth in Ewing’s sarcoma cell lines but not non-Ewing’s cells." (PMID 36194562, 2022).
cancer (4 papers, 2021 to 2025). A tumor composed of atypical neoplastic, often pleomorphic cells that invade other tissues. "The recent studies linking AHDC1 to early epithelial morphogenesis, cancer pathogenesis, and metabolic regulation expand its significance beyond neural development, indicating a broader impact on human physiology and disease." (PMID 40844525, 2025). "We found an increased abundance of the transcription factors AHDC1 and ERF, as well as proteins associated with cancer stemness (AQP5 and ASB6), which were higher expressed in SBT-MP when compared to SBT." (PMID 38014221, 2023). "However, the molecular mechanisms for AHDC1 in cancer cells are still unclear." (PMID 36194562, 2022). "Feng and colleagues, in addition to unveiling a connection between AHDC1 expression and cancer pathogenesis, identified a long noncoding RNA, LINC0113328, acting as a competing endogenous RNA (ceRNA) subtracting miR-4784 from the AHDC1 3’ UTR and therefore increasing its expression level." (PMID 40844525, 2025).
neurodevelopmental disorder (4 papers, 2021 to 2025). A behavioral and cognitive disorder with onset during the developmental period that involves impaired or aberrant development of intellectual, motor, or social functions. "Despite these emerging insights, knowledge of AHDC1 remains very limited, while recent studies suggest that its functions are critical for mammalian development, neurodevelopmental disorders and beyond." (PMID 40844525, 2025).
AHDC1 also shares sentences with these, for which no sentence is quoted: obstructive sleep apnea (3 papers); autism (2); craniosynostosis (2); Failure to thrive (2); genetic disorder (2); atypical Rett syndrome (1); cerebrooculofacioskeletal syndrome 1 (1); Cockayne syndrome B (1); Esotropia (1); Hepatic steatosis (1); infectious disease (1); Insulin resistance (1); kidney disease (1); Lissencephaly (1); Macrocephaly (1); metabolic disorder (1); Miller-Dieker syndrome (1); neurological disorders (1); osteosarcoma (1); pancreatic cancer (1); Phelan-McDermid syndrome (1); scoliosis (1); spinocerebellar ataxia type 1 (1); tuberous sclerosis (1); tumor (1).